C1QBP (complement C1q binding protein)
Diseases named in the same sentence as C1QBP in open-access papers (continued):
Sharing a sentence is not in itself a finding about the gene and the disease.
renal cell carcinoma (9 papers, 2017 to 2025). "C1QBP promotes the catabolism of hypoxanthine and elevates the apoptosis of renal cell carcinoma cells by modulating xanthine dehydrogenase (XDH)-mediated oxygen species (ROS) generation." (PMID 40454173, 2025). "The protein expression of YB-1 is negatively correlated with C1QBP expression in human renal cell carcinoma (RCC) clinical tissues, as shown by immunohistochemical staining." (PMID 35406781, 2022). "C1QBP regulates YBX1 and suppresses androgen receptor (AR)-enhanced invasion of renal cell carcinoma cells." (PMID 40799245, 2025). "Interactions between C1QBP and YBX1 result in decreased C1QBP levels, enhancing YBX1 phosphorylation and nuclear translocation in renal cell carcinoma." (PMID 40799245, 2025). "Complement component 1q subcomponent binding protein (C1QBP) is a ubiquitously expressed cellular protein and can be upregulated or activated in a variety of malignant tumors, including those from thyroid, colon and breast, but its role remains unclear in renal cell carcinoma (RCC)." (PMID 28428626, 2017). "However, the role of C1QBP in metabolism, oxidative stress, and apoptosis of renal cell carcinoma (RCC) cells have not yet been explored." (PMID 35693733, 2022).
cervical carcinoma (8 papers, 2012 to 2025). A carcinoma arising from either the exocervical squamous epithelium or the endocervical glandular epithelium. "An association between patient survival and C1QBP expression was previously reported in breast, ovarian, endometrial, and cervical cancer." (PMID 30991713, 2019). "C1QBP promoter methylation could impede the host immune response by modifying interleukin 6 production and dendritic cell metabolism and maturation; activity important in cervical cancer cell progression." (PMID 32025240, 2020).
triple-negative breast carcinoma (8 papers, 2017 to 2025). An invasive breast carcinoma which is negative for expression of estrogen receptor (ER), progesterone receptor (PR), and human epidermal growth factor receptor 2 (HER2). "Complement 1q binding protein (C1QBP/HABP1/p32/gC1qR) has been found to be overexpressed in triple-negative breast cancer (TNBC)." (PMID 33708767, 2021).
colon cancer (7 papers, 2018 to 2024). "This study aimed to evaluate the effects of a drug with p32/C1QBP as a specific target to understand the molecular and cellular mechanisms underlying the oncogenic functions of C1QBP in colon cancer cells." (PMID 38473963, 2024). "In this study, we aimed to evaluate the effects of a drug with p32/C1QBP as a specific target to understand the molecular and cellular mechanisms underlying the oncogenic functions of C1QBP in colon cancer cells." (PMID 38473963, 2024). "C1QBP has also been implicated in Akt/mTOR signaling, which affects the migration capability of colon cancer cells." (PMID 36674861, 2023). "We have previously demonstrated that the p32/C1QBP protein is an essential promoter of migration, chemoresistance, clonogenic, and tumorigenic capacity in colon cancer cells." (PMID 38473963, 2024). "Here, we show that the specific pharmacological inhibition of C1QBP with the small molecule M36 significantly decreased the viability rate, clonogenic capacity, and proliferation rate of different colon cancer cell lines in a dose-dependent manner." (PMID 38473963, 2024). "Previously, we demonstrated that C1QBP is an essential promoter of migration, chemoresistance, clonogenic, and tumorigenic capacity in colon cancer cells." (PMID 38473963, 2024). "Altogether, these results reinforce the notion that the pharmacological inhibition of the p32/C1QBP protein with M36 has a cytostatic effect on colon cancer cells." (PMID 38473963, 2024). "The protein p32 (C1QBP) is a multifunctional and multicompartmental homotrimer that is overexpressed in many cancer types, including colon cancer." (PMID 38473963, 2024). "Here, we show that p32/C1QBP induces a pro-growth effect on colon cancer cells by regulating the activation of signaling pathways triggered by growth factors and functioning as a key modulator of mitochondrial integrity and dynamics." (PMID 38473963, 2024). "Analysis with the Oncomine and GENT databases showed that expression of C1QBP was apparently augmented in multiple cancers including the most common breast, lung, and colon cancers." (PMID 30991713, 2019). "Thus, combined with autophagy inhibitors, p32/C1QBP inhibition shows promise as an effective colon cancer treatment." (PMID 38473963, 2024). "Therefore, we can conclude that the pharmacological inhibition of C1QBP with M36 induced a decrease in the viability rate of colon cancer cells with high expression levels of p32/C1QBP." (PMID 38473963, 2024). "Altogether, our results reinforce that C1QBP is an important oncogene target and that M36 may be a promising therapeutic drug for the treatment of colon cancer." (PMID 38473963, 2024). "Therefore, we chose breast, lung, and colon cancers; in addition, bladder cancers and lymphoma were chosen among the other cancers in which C1QBP expression was higher than in normal tissue for further systematic expression and prognosis analysis." (PMID 30991713, 2019). "Elevated C1QBP expression was observed in several colon cancer cell lines and patient tissues." (PMID 30991713, 2019). "It was reported that ApoA-I established antitumor properties by interacting with C1QBP in colon cancer, and ApoA-I could also inhibit colitis-propelled carcinogenesis and modulate tumorigenicity and immunogenicity." (PMID 30510601, 2018). "In addition, we recently reported that the knockdown of p32/C1QBP sensitizes colon cancer cells to cell death induced by oxidative stress and chemotherapeutic agents, but not to cell death induced by nutritional stress, which potently induces autophagy in colon cancer cells." (PMID 38473963, 2024). "Interestingly, the most marked effect was observed in the RKO colon cancer cell line (IC50 = 55.86 μM), which presented the highest C1QBP expression level among the evaluated cell types." (PMID 38473963, 2024). "However, the correlation between C1QBP expression and colon cancer patient survival has not yet been investigated." (PMID 30991713, 2019).
colon cancer (continued). "The effects of the inhibitor of C1QBP were cytostatic and non-cytotoxic, inducing a decreased activation rate of critical pro-malignant and mitogenic cellular pathways such as Akt-mTOR and MAPK in RKO colon cancer cells." (PMID 38473963, 2024).
melanoma (7 papers, 2016 to 2025). A malignant, usually aggressive tumor composed of atypical, neoplastic melanocytes. "Due to these roles, C1QBP presents a promising therapeutic target for various tumors, including melanoma, breast cancer, and colorectal cancer." (PMID 40736231, 2025). "C1QBP is expressed at high levels in a significant number of tumor types, including melanoma, colon, ovarian, gastric, prostate, brain, and breast, compared with their nonmalignant counterparts." (PMID 36467687, 2022). "It was originally identified as a melanoma-specific lncRNA that promotes maturation of mitochondrial 16S rRNA through interaction with complement C1q binding protein (C1QBP) and supports cell survival." (PMID 34483148, 2021). "In addition, we established stable Pa28γ-silenced B16 cells, a mouse melanoma cell line, and found that the level of C1qbp protein was decreased in Pa28γ-silenced B16 cells." (PMID 40736231, 2025). "C1QBP-integrin interaction results in transcriptional upregulation of MT1-MMP expression and finally MMP-2 activation, leading to enhanced tumorigenicity and cell migration in B16F10 melanoma cell line." (PMID 36467687, 2022).
prostate carcinoma (6 papers, 2016 to 2025). A carcinoma that arises from epithelial cells of the prostate gland. "Very recently, C1QBP has been associated with fatty acid degradation, where silencing of C1QBP has been shown to reduce lipid droplets and triglycerides in prostate cancer cells." (PMID 36674861, 2023). "Our results also corroborate with previous reports, wherein downregulation of C1QBP was observed to decrease cell proliferation in breast and prostate cancer cells." (PMID 36674861, 2023). "In concurrence, C1QBP silencing was reported to induce G1 to S phase arrest in prostate cancer cells." (PMID 36674861, 2023). "The expression of C1QBP is up-regulated in human tumors and correlates with poor prognosis in breast and prostate cancer and over-expression of C1QBP results in enhanced cell proliferation consistent with it being pro-tumorigenic." (PMID 26999212, 2016). "A study reported that C1QBP silencing induces G1 to S phase arrest in prostate cancer cells." (PMID 40454173, 2025).
cardiomyopathy (5 papers, 2017 to 2024). A disease of the heart muscle or myocardium proper. "Biallelic deficiency of the MYC target gene—complement component 1 Q subcomponent-binding protein, mitochondrial (C1QBP)—causes mitochondrial respiratory-chain deficiencies and severe cardiomyopathy." (PMID 39457090, 2024). "In conclusion, mitochondrial dysfunction caused by C1QBP deficiency affects cellular homeostasis and induces a protective response against cardiomyopathy." (PMID 35310974, 2022). "Cardiomyocyte‐specific loss of mitochondrial p32/C1qbp (p32cKO) caused cardiomyopathy owing to loss of mitochondrial translation, OXPHOS dysfunction, and structural impairment at 2 months of age, followed by death 10 months later." (PMID 33528041, 2021). "Cardiomyocyte‐specific loss of mitochondrial p32/C1qbp causes cardiomyopathy owing to loss of mitochondrial translation and impaired mitochondrial structure." (PMID 33528041, 2021).
hepatocellular carcinoma (5 papers, 2015 to 2025). A malignant tumor that arises from hepatocytes. "Previous studies have found that stable knockdown of the C1QBP gene has also been previously shown to inhibit apoptosis in hepatocellular carcinoma cells." (PMID 40454173, 2025). "Similarly, overexpression of C1QBP in liver carcinoma cells has likewise been reported to increase cell proliferation." (PMID 36674861, 2023).
cervical squamous cell carcinoma (4 papers, 2012 to 2020). A squamous cell carcinoma arising from the cervical epithelium. "But it has also been documented that C1QBP is significantly decreased in human cervical squamous cell carcinoma tissues relative to normal cervix tissues and inhibits viability, migration and proliferation of cervical squamous cells carcinoma via the p38 MAPK signaling pathway." (PMID 28428626, 2017).
glioma (4 papers, 2021 to 2023). A benign or malignant brain and spinal cord tumor that arises from glial cells (astrocytes, oligodendrocytes, ependymal cells). "Considering that C1QBP is be specifically expressed on the surface of glioma cells, it is regarded as a suitable tumor associated antigen (TAA) for redirected chimeric antigen receptor (CAR) T cell therapy." (PMID 36467687, 2022). "In this study, we identify p32/gC1qR/HABP/C1qBP to be specifically expressed on the surface of glioma cells, making it a suitable tumor associated antigen for redirected CAR T cell therapy." (PMID 34127674, 2021). "For example, upregulation of C1qbp mRNA has been detected in low and high-grade gliomas, especially recurrent glioblastoma (GBM)." (PMID 36467687, 2022). "Their study focused on designing CAR T cells targeting C1QBP positive glioma cells." (PMID 36467687, 2022). "C1QBP silencing in glutamine-addicted glioma cells induced resistance to glutamine deprivation." (PMID 36467687, 2022). "In addition, they further demonstrated that M36 impedes the growth of glioma cells and patient-derived glioma stem cells in culture due to C1QBP genetic knockdown." (PMID 36467687, 2022). "On the other hand, attenuation of C1QBP expression stunted glioma cells’ growth." (PMID 36467687, 2022). "A primary screening assay employing a glutamine-addicted glioma cell line identified a hit compound called M36, which could bind and inhibit C1QBP located on the cellular membrane and in the mitochondria." (PMID 36467687, 2022). "Thus, CAR T cells targeting C1QBP may serve as a therapeutic option for glioblastoma patients through specifically recognizing and eliminating C1QBP expressing glioma cells and tumor derived endothelial cells, finally controlling tumor growth in orthotopic syngeneic and xenograft mouse models." (PMID 36467687, 2022). "They found that the CAR T cells targeting C1QBP reduced tumor vascularization and extended the overall survival of mice bearing gliomas, thus providing proof-of-principle evidence that C1QBP-CAR T cells can recognize and eliminate not only glioma cells but also tumor endothelial cells." (PMID 36467687, 2022).
breast tumor (3 papers, 2018 to 2023). "Moreover, another tumor-homing peptide, LyP-1 (CGNKRTRGC), capable of targeting the cell surface of localized C1QBP, has been used to deliver nanoparticles to breast tumors overexpressing C1QBP and has shown efficacy in vivo." (PMID 36467687, 2022).
influenza infection (3 papers, 2020 to 2024). "Previous study showed that two complement-related SNPs, rare TT genotype of CD55 and rare AA genotype of C1QBP, were associated with increased death risk of influenza, which indicated that mutations related to immunity may affect the prognosis." (PMID 39014398, 2024). "Two SNPs in the C1QBP (rs3786054) and FCGR2A (rs1801274) genes have been reported to be associated with the cases of severe influenza in Mexico in 2009." (PMID 33766078, 2021). "Several polymorphisms which have been known for the susceptibility to influenza infection include CD55, C1QBP, FCGR2A, IFITM3, TNF, RPAIN, LTA and KIR." (PMID 33766078, 2021).
laryngeal carcinoma (3 papers, 2022 to 2024). Carcinoma that arises from the laryngeal epithelium. "CircMTCL1 activates the expression of C1QBP and reduces the phosphorylation of β‐catenin protein by directly recruiting protein C1QBP, which activates the Wnt/β‐catenin signaling axis and exacerbates tumor growth and migration in laryngeal cancer." (PMID 39584047, 2024). "Unlike circNR3C2, CircMTCL1 was reported to promote complement C1q-binding protein (C1QBP)-dependent ubiquitin degradation to play its oncogenic function in laryngeal carcinoma." (PMID 36671487, 2023).
mesothelioma (3 papers, 2019 to 2024). A usually malignant and aggressive neoplasm of the mesothelium which is often associated with exposure to asbestos. "Examination of this data set for gC1qR gene (C1QBP) expression in mesothelioma (n = 85) revealed that C1QBP expression was not correlated with OS [HR 1.08 (0.67–1.74, p = 0.755)]." (PMID 31681580, 2019).
Multiple Myeloma (3 papers, 2019 to 2024). "Compared to the expression level in the normal counterpart, expression of C1QBP was upregulated in bladder, brain and central nervous system (CNS), colorectal, gastric, head and neck and kidney cancers, as well as lymphoma, myeloma, and some other cancers." (PMID 30991713, 2019). "From the Oncomine analyses, C1QBP expression was found to be upregulated in various other cancers including brain, gastric, prostate, kidney, myeloma, and ovarian cancers." (PMID 30991713, 2019).
Stroke (3 papers, 2023 to 2025). Sudden impairment of blood flow to a part of the brain due to occlusion or rupture of an artery to the brain. "In this dataset, we observed a significant decrease in LRG expression levels at 14 days post-stroke compared to 1-day post-stroke, with C1qbp and Myc showing the most marked reductions, nearly returning to sham group levels." (PMID 40292254, 2025). "ELISA detected the expression of C1QBP, RPS28 and RNASEL proteins in stroke patients, and the proportion of neutrophils was significantly increased in the high-risk group." (PMID 39290696, 2024). "Notably, C1qbp expression remained relatively stable across MG1 in both MCAO and sham groups 1-day post-stroke." (PMID 40292254, 2025).
Arrhythmia (2 papers, 2013 to 2024). Any cardiac rhythm other than the normal sinus rhythm. "Four proteins (GJA1, TPM2, GJA5 and C1QBP) were related with cardiac arrhythmias, cardiac dysfunction and cardiac cell damage, and might also be responsible for DCM." (PMID 23940716, 2013).
atherosclerosis (2 papers, 2016 to 2024). A disease characterized by the build-up of fatty material and calcium deposition in the arterial wall resulting in partial or complete occlusion of the arterial lumen. "In conclusion, macrophages interacting with CD8T promote atherosclerosis development via the C1q–C1qbp axis." (PMID 39345351, 2024). "We explored the role of the C1q–C1qbp axis in atherosclerosis progression." (PMID 39345351, 2024). "Overall, the C1q–C1qbp axis exerted a positive effect on atherosclerosis." (PMID 39345351, 2024). "However, whether the C1q–C1qbp axis between other cell subsets also promotes atherosclerosis remains to be clarified." (PMID 39345351, 2024).
bladder cancer (2 papers, 2019 to 2020). "Gene ontology and pathway analysis of commonly differentially coexpressed genes with C1QBP in breast, lung, colon, and bladder cancers as well as lymphoma revealed the C1QBP-correlated pathways in these cancers." (PMID 30991713, 2019). "Among analyzed cancers in this study, the expression of C1QBP was more than the 2.5-fold augmented in bladder cancer and lymphoma compared to their normal counterparts, which were bigger than other cancers." (PMID 30991713, 2019). "Level of C1QBP expression was positively correlated with copy number alterations and negatively correlated with patient survival in breast, lung, colon, and bladder cancers as well as lymphoma." (PMID 30991713, 2019). "C1QBP mRNA expression was highly upregulated in bladder cancer compared to the normal counterparts according to both the Oncomine and GENT databases." (PMID 30991713, 2019). "Therefore, we sought to systematically investigate the expression of C1QBP to evaluate the change of C1QBP expression and the relationship with patient survival and affected pathways in breast, lung, colon, and bladder cancers as well as lymphoma." (PMID 30991713, 2019).
endometrial cancer (2 papers, 2018 to 2025). Primary or metastatic malignant neoplasm involving the endometrium (mucous membrane that lines the endometrial cavity). "C1qbp was significantly enriched in endometrial cancer, glyoxylate and dicarboxylate metabolism, and proteasome pathways." (PMID 40292254, 2025).
glioblastoma (2 papers, 2019 to 2022). The most malignant astrocytic tumor (WHO grade IV). "TCGA database analyses also showed an upregulation in C1QBP expression in various other cancers including cholangio, glioblastoma multiforme, pancreatic, rectum, stomach, testicular germ cell, and thymoma cancers." (PMID 30991713, 2019).